MIR592 (microRNA 592)
Synonyms: hsa-mir-592; MIRN592; mir-592
Gene: MicroRNA gene on chromosome 7 (127,058,088 to 127,058,184, reverse strand). Ensembl gene ENSG00000207692.
Gene Ontology:
Biological process: miRNA-mediated post-transcriptional gene silencing
Cellular component: RISC complex
Homologues: Orthologues: chimpanzee ptr-mir-592 (100% identical), macaque MIR592 (100% identical), pig MIR592 (97% identical), guinea pig MIR592 (96% identical), mouse Mir592 (95% identical), dog MIR592 (94% identical), rabbit MIR592 (62% identical).